IL6 (interleukin 6)
Diseases named in the same sentence as IL6 in open-access papers (continued):
Sharing a sentence is not in itself a finding about the gene and the disease.
tumor (continued). "By further exploring the mechanism, our previous work suggested that IL-6 was associated with sorafenib-induced tumor invasiveness but only through IL-6, and its subsequent signaling pathways such as PI3K/JAK/STAT may not fully explain the time and dosage-specific effects of sorafenib on HCC cells." (PMID 37476196, 2023). "Furthermore, tumor-associated CD4+ T cells can also release IL-6 in ccRCC." (PMID 37190141, 2023). "Some authors correlate IL-6 levels with tumor stage, the metastasis survival rate, or apoptosis in various types of cancer, such as breast or colon, while the production of IL-8 has been linked to pro-tumorigenic roles which influence the tumor microenvironment." (PMID 36986093, 2023). "STK11 mutations are often associated with an “immune-cold” tumor microenvironment with low PD-L1 and T-cell densities, high granulocyte colony-stimulating factor and IL-8 family cytokines, and production of neutrophil-like cells and myeloid cell-recruiting chemokines such as IL-6." (PMID 36430528, 2022). "Therefore, we focused on the influence of IL-6 on tumour development in IL-9-deficient animals." (PMID 35793807, 2022). "In addition, TLR4 on macrophages promoted the growth of steatohepatitis-related HCC in mice, as the number of macrophages expressing Ly6C was increased and these cells were associated with inflammation and tumor progression, generating increased amounts of IL-6 and TNFα in response to LPS." (PMID 35008390, 2022). "IL-6 levels were elevated both in the tumors and serum of tumor-bearing mice which was also associated with increased protein concentrations of the IL-6 regulated transcription factor pSTAT3 and increased expression of downstream targets of IL-6 signaling in the liver (e.g., Stat3)." (PMID 35663547, 2022). "Notably, the reduced burdens of cancer cells in glucan-administered mice resulted in lower serum IL-1β and IL-6 (the cytokines that might be associated with tumor growth)." (PMID 36142859, 2022). "Moreover, Th17 numbers were increased in MDS patients, with greater expansion in low-risk disease, denoting the auto-reactive, possible anti-tumor nature of the process, whereas Th22 cells were increased in high-risk disease, correlating with increased IL-6 and TNF-a." (PMID 35735633, 2022). "Additionally, IL‐6 is suggested to contribute to the mitochondrial abnormalities associated with tumour growth, as neutralising IL‐6 antibodies restored altered peroxisome proliferator‐activated receptor‐gamma coactivator (PGC)‐1α levels and mitochondrial content." (PMID 36251564, 2022). "IL-6 is known to increase resistance to ionizing radiation and cisplatin that may explain why there was a positive association between IL-6 dynamics and early treatment responses regarding tumor-associated hypoxia." (PMID 34773163, 2022). "Furthermore, scientists observed a higher amount of M2-associated mRNAs for e.g., IL-10, Arg-1, and TGFβ and the reduction of M1-associated mRNAs such as TNF-α, IL-6, and IL-12 in tumor-associated macrophages from EC specimens, in comparison to macrophages obtained from healthy specimens." (PMID 35563789, 2022). "Besides IL-6 and IL-8 values, baseline albumin value ≥ 17 g/L (p = 0.008) and tumor diameter ≥ 65 mm (p = 0.021) were associated with overall survival, whereas there was a trend for better survival in patients with total bilirubin < 17 g/L (p = 0.058) and portal vein invasion (p = 0.099)." (PMID 33855585, 2022). "Therefore, we sought to assess whether tumor-associated NLRP3 activity also affects the IL-1β/IL-6/STAT3 axis in host myeloid cells." (PMID 34531850, 2021). "Additionally, low IL-6-expressing tumours are associated with an epithelial signature." (PMID 34361105, 2021).
tumor (continued). "Pathogenic microorganisms and tumor cells can be eliminated by M1 macrophages by acute proinflammatory response, immune activation reaction, and cytophagy through the release of proinflammatory factors, such as NO, IL-1β, IL-6, TNF-α, and chemokines such as CCL2, CCL3, CCL5, CXCL9, and CXCL10." (PMID 34506209, 2021). "Thus, significant enrichment of macrophages M1 activated CD4 memory T cells in the tumor microenvironment and that of the hallmark IL6/JAK/STAT3 signaling pathway in tumor tissues indicate initiation, growth, and escape of OSCC-GB tumor cells from host immune response." (PMID 33980865, 2021). "Hence, inflammatory-associated factors, such as IL-6 and SDF1α, might not only play roles in tumor progression on this therapy but also be potential novel targets for HCC." (PMID 34948424, 2021). "This study suggests that the SNPs rs1800795 IL-6 and rs4073 IL-8, and serum levels of these interleukins, may be probable factors associated with disease progression and survival in NB, providing a link between the host environment and potential tumor growth." (PMID 33573284, 2021). "Similarly, IL-6 derived from glioblastoma cells induced PD-L1 in tumour-associated myeloid cells." (PMID 34047814, 2021). "Therefore, physicians should bear in mind that watchful observation is needed whether tocilizumab can control tumor progression despite the amelioration of PIS associated with the attenuated effect of IL-6 on AFH." (PMID 34221525, 2021). "Their contribution to prognosis may be more related to increased levels of some cytokines they secrete, specifically vascular endothelial growth factor and interleukins including IL-6 and IL-8 known to be associated with angiogenesis promoting tumour growth, along with MPE formation." (PMID 33901252, 2021). "The autocrine and paracrine action of IL-6 is associated with multiple signaling pathways that support not only aggressive features of cancer cells such as invasion, migration and metastasis, but also tumor growth, survival angiogenesis, regulation of immune response and chemoresistance." (PMID 34445170, 2021). "Additionally, the tumor-promoting effects of IL-6 involve increases in MDSCs and Th17 cells, suppression of DCs and cytotoxic T cells, and phenotypic switching of tumor-associated macrophages (TAM) from an antitumor M1 phenotype to an immunosuppressive M2 phenotype." (PMID 33981768, 2021). "Interestingly, IL-6 is a component frequently implicated in tumor-supporting pathways." (PMID 33287630, 2021). "Notably, tumor-associated macrophage-derived IL-6 binds to receptor/glycoprotein 130 (gp130) and upregulates Janus kinase (JAK)-STAT3 signaling in CRC cells, leading to increased EMT and chemoresistance, which promotes the proliferation and invasion of CRC cells." (PMID 34394377, 2021). "To corroborate the notion that TGFβ acts as a major tumor-associated cytokines in the generation of decidual-like/anergic NK cells, we further tested the effects of TGFβ on NK cell polarization, as compared to IL-6, another relevant cytokine present in the tumor micro- and macro-environment." (PMID 34638439, 2021). "Therefore, the KS tumor environment and associated cytokines which are elevated in KS patients, such as IL-6, may also contribute towards KS immune evasion through the neutrophil pathway." (PMID 33294468, 2020). "In the present study, according to the results of the IHC analysis, we speculated that in patients with FOBT-positivity, local TIM (such as TAM, TNF-α, IL-6) is conducive to tumor proliferation and vascularization and is associated with adjuvant chemotherapy resistance." (PMID 33643891, 2020). "In addition to classic signaling, transsignaling also plays an important role in the TME to recruit tumor-associated stromal cells; therefore, further study is needed to investigate whether the IL-6 transsignaling pathway is involved in the process here." (PMID 32855767, 2020).
tumor (continued). "Moreover, IL-6 was linked with natural killer cell dysfunction, which may provide a mechanism of tumor escape from immune surveillance." (PMID 32266003, 2020). "Based on a previously published work, the Authors speculated that the concomitant loss of STK11 together with mutations in an oncogenic pathway (KRAS/RAF) promotes IL-6 secretion by tumor cells, which, in turn, can determine the recruitment of neutrophils in the tumor microenvironment." (PMID 33168050, 2020). "Importantly, reduced caloric intake and regular exercise have been shown to reduce the serum concentrations of IL-6, TNFα and are associated with reduced activity of tumor-promoting transcription factors, including activator protein (AP)-1, STAT3 and NF-kB in various tissues." (PMID 32825010, 2020). "The differentiation of megakaryocytes to platelets could be triggered by the tumor-associated inflammatory mediators, such as IL-1, IL-3, and IL-6 that accelerate tumor cell growth and dissemination; in addition, platelets cooperate to protect circulating cancer cells from the immune system." (PMID 31261762, 2019). "Interestingly, IL-6 has been implicated to stimulate a defective angiogenesis in tumor models." (PMID 30809262, 2019). "Moreover, malajusted miR- 155-5p/C/EBPβ/IL6 signaling in tumor-associated macrophage could induce chemoresistance by regulating the IL6R/STAT3/miR-204-5p axis." (PMID 30897064, 2019). "However, if experimental funds are permitted, further studies will be required based on the syngeneic model that is more ideal to demonstrate anti-tumor immune response to explain the specific underlying mechanism by which HOTTIP/IL-6/PD-L1 network influences OS." (PMID 31533774, 2019). "Therefore, the attenuation of mTOR signaling in the skeletal muscle of tumor-bearing mice might be caused by the activation of STAT3 signaling through the enhanced production of adipocyte IL-6." (PMID 30555329, 2018). "Therefore, IL-6 in the tumor-associated microenvironment might be derived from both M2 macrophages and cancer cells based on this study." (PMID 30266897, 2018). "Inhibition of the activation of STAT3, e.g. by the anti-IL6R monoclonal antibody Tocilizumab, is known to down-regulate the immune suppression caused by tumor cells, and inhibition of IL-6 signaling may be a therapeutic for patients with cancer when IL-6 is over-expressed." (PMID 30038723, 2018). "Notably, M2 macrophages functionally overlap with tumour-associated macrophages, indicating that IL-6 might have a detrimental role in carcinogenesis." (PMID 29695802, 2018). "However, anti-IL-6 and sGP130Fc treatment in lean mice reduced afflicted colonic area, which is in line with a previous report, demonstrating IL-6 deficiency reducing tumour area in CAC25." (PMID 29695802, 2018). "Tumor-associated macrophages play a role in β-adrenergic signaling pathways, by accelerating angiogenesis, chemokine secretion to attract tumor cells, secretion of pro-inflammatory cytokines (IL-1, IL-6, IL-8, and tumor necrosis factor (TNF)-α) and escape of anti-tumor responses." (PMID 29334991, 2018). "Therefore, ROS may activate NF-κB to cause GC cells and cancer-associated fibroblast cells (CAFs) to release IL-6, thus mediating tumor metastasis and self-renewal that will consequently facilitate CSC self-renewal and maintenance." (PMID 29770167, 2018). "Tumor-associated macrophages (TAMs) were shown to promote tumor growth in part by suppressing immune response to cancer cells but also by producing specific cytokines, most of which are dependent on IKKβ-mediated canonical NF-κB signaling (e.g., IL-6) that enhance tumor cell growth in vivo." (PMID 29601548, 2018). "All these findings indicate that IL‐6‐expressing tumors are more resistant to the cytotoxic action of NK cells, and confirmed the in vitro data suggesting the importance of IL‐6 signaling in determining the susceptibility of tumor cells to cytotoxic actions of NK cells." (PMID 28865178, 2018).
tumor (continued). "Importantly, increases in TNFα, IL-12p70 and IL-2 are not merely consequent of enhanced immune cell presence, as a number of other cytokines were unaltered by ibuprofen treatment including those associated with tumor associated macrophages, monocytes and M2 polarized macrophages [IL-4, IL-6, IL-10]." (PMID 30285905, 2018). "The goal of the authors of the scale was to reflect the tumor mass and degree of renal involvement by measuring serum β2-microglobulin concentration and indirectly analyzing bone marrow microenvironment via albumin concentration, which is closely associated with IL-6 concentration." (PMID 29844872, 2018). "Therefore, the knock-out of IL-6 may be associated with inhibited tumor angiogenesis and tumor growth." (PMID 29100435, 2017). "Thus, IL-6 could be tumor derived, or indeed released from tumor associated M1 macrophages and neutrophils." (PMID 28402963, 2017). "In light of the behavioural effect of 5-ASA/SP treatment on the SPT despite failure to prevent tumour-associated increases in IL-1β and IL-6, an investigation of a wider array of inflammatory markers might help clarify the observed behavioural effects of these drugs in our model." (PMID 28120908, 2017). "In addition, nuclear myoferlin expression was directly associated with high IL-6 expression in the primary tumor samples thereby suggesting that IL-6 might be involved in promoting the nuclear translocation of myoferlin." (PMID 26919244, 2016). "Notably, cDC2s, either isolated from the tumour site or from tdLNs, were unique in their Th17-inducing capacity, which is likely to be linked with their high production of the Th17-inducing cytokines IL-23, IL-1β and IL-6." (PMID 28008905, 2016). "Thus, this suggests that the TERT mutations and increased telomerase activity may maintain a tumor phenotype by stimulating an inflammatory response and angiogenesis as suggested by the increased IL-6 levels." (PMID 26143636, 2015). "To better understand the signaling mechanisms involved in the formation of PCa-associated stroma and which tumor derived-stimuli are able to induce the reactive phenotype seen in vivo, we extended gene expression analysis on fibroblasts activated in vitro with TGFβ or IL6." (PMID 26375444, 2015). "When type 2 cells are introduced into mice, their production of TNF-α, IL-1α, or CCL5 is expected to induce the production of cytokines such as IL-6 and IL-8 in the associated fibroblast-like cells, which might in turn function as paracrine factors in tumor formation." (PMID 25673149, 2015). "Moreover, in the model of tumor-induced fatigue in mice seen earlier, fatigue was associated with increased levels of IL-1 and IL-6 in the brain, and treatment with minocycline, an anti-inflammatory agent, improved grip strength without reducing tumor growth or muscle mass." (PMID 26435495, 2015). "In addition, cancer-associated fibroblasts mediate tumour-enhancing inflammation and produce IL-6." (PMID 24467886, 2014). "Importantly, IL-6 production occurs as a result of p38 mitogen-activated protein kinase (p38MAPK) activation in tumor-associated endothelial cells rapidly after genotoxicity, an acute cytokine release that was also observed in treated human endothelial and hepatocellular carcinoma cells." (PMID 25185441, 2014). "However, even though IL-6 seems to be associated with tumor progression, its relationship with the AR is convoluted and IL-6/STAT3 can have both pro and anti-proliferative effects on tumor cells as that depends on AR status of PCa cells well as activity/crosstalk from other pathways." (PMID 24722453, 2014). "Therefore, in addition to increased cell death, slower tumor regrowth associated with attenuated angiogenesis may contribute, in part, to the radiosensitization induced by IL-6 inhibition in vivo." (PMID 23806095, 2013).
tumor (continued). "IL-6, which is produced mainly by mononuclear cells, macrophages and a smaller percentage of fibroblasts, endothelial cells, T and B lymphocytes, chondrocytes and amnion cells, is a pleiotropic cytokine that causes carcinogenesis, promotes tumor growth and facilitates tumor cell metastasis." (PMID 23922983, 2013). "Furthermore, STAT3 activation by conditioned medium of tumor-associated fibroblasts could be blocked by berberine or antibodies against IL-6 and IL-6R." (PMID 24380387, 2013). "Besides, berberine could abrogate the activation of STAT3 in NPC cells induced by the IL-6 secreted from tumor-associated fibroblasts." (PMID 24380387, 2013). "Induced expression of IL-6 in EMT6 cancer cells caused recruitment of MDSCs in lymphoid organs, metastatic target organs and primary tumor sites comparable to that caused by metastasizing 4T1 cancer cells, which implies that IL-6 or downstream signaling may be involved in this process." (PMID 24021059, 2013). "Among these, Interleukin-6 (IL-6) has a fundamental role in the regulation of proliferation, apoptosis, angiogenesis and differentiation in many cell types and it is also implicated in the development and progression of several forms of tumours including that of the prostate." (PMID 19242540, 2009). "Furthermore, IL-6 has been implicated in autocrine loops promoting tumor growth." (PMID 19582164, 2009). "The immune cells may even increase the potential of cancer cells to progress, proliferate, and metastasise, that is, the tumour-associated macrophages release metalloproteinases for local tissue destruction and interleukin (IL)-6 and IL-8 for endothelial cell invasion into the tumour." (PMID 18594539, 2008). "High YIF1B coupled with activation of the IL-6/JAK pathway produces a positive feedback loop in which tumor proliferation/metastasis is enhanced, as is T cell immunosuppression, eventually culminating in profound immunosuppression and tumor growth." (PMID 42253503, 2026). "TGN treatment also decreases the secretion of TGFβ3, IL-6, and VEGF by CAF-containing tumor-like constructs, all of which facilitate tumor-associated angiogenesis, drug resistance, and metastasis." (PMID 41596251, 2026). "Next, we found that protein content of IL-6 was ~5-fold greater in muscle from wildtype tumour-bearing mice compared to control mice, and GPx4 overexpression prevented this increase in IL-6." (PMID 41854231, 2026). "Regarding the production of TNF by MCs, both TNF stored in the granules and that produced through protein synthesis stimulate the production of other cytokines, such as IL-1 and IL-6, inducing apoptosis and counteracting tumor growth." (PMID 41596472, 2026). "At the same time, miR-32-5p increases production of M1-type proinflammatory factors such as CD86, CCL2, tumor necrosis factor-α (TNF-α), and interleukin-6 (IL-6), thereby enabling macrophage polarization toward tumor-suppressive phenotype." (PMID 41608526, 2026). "IL-6 and B-cell lymphoma 2 showed downregulated expression in tumor tissues, while cyclin-dependent kinase 1, cyclin-dependent kinase 2, cyclin B1, Erb-B2 receptor tyrosine kinase 2, and cyclin B2 were upregulated." (PMID 41650055, 2026). "The interaction of MAPK/ERK signalling pathway with NF-κB increases the production of pro inflammatory cytokines, like IL-6 to support the survival of tumour cells from circulation." (PMID 41476776, 2026). "RT-qPCR analysis demonstrated upregulation of anti-tumor inflammatory cytokines (IL-6, TNF-α, iNOS) and concurrent downregulation of pro-tumor factors (IL-4, IL-10), confirming successful M2 to M1 phenotype conversion with efficacy comparable to LPS treatment." (PMID 41560805, 2026). "The effects of IL-6 can be direct on tumor cells, as well as indirect through the promotion of angiogenesis, invasiveness, and metastasis." (PMID 41596451, 2026). "Single-cell transcriptomics suggests the role of interleukin 6 in direct communication between tumor cells and BAMs." (PMID 42196381, 2026).